RN7SL646P (RNA, 7SL, cytoplasmic 646, pseudogene)
Gene: Miscellaneous RNA gene on chromosome 5 (178,377,924 to 178,378,220, forward strand). Ensembl gene ENSG00000242341.
Homologues: Orthologues: chimpanzee Metazoa_SRP (98% identical), macaque Metazoa_SRP (91% identical). Paralogues in human: RN7SL1 (83% identical), RN7SL2 (82% identical), RN7SL3 (82% identical), RN7SL357P (81% identical), RN7SL218P (80% identical), RN7SL296P (79% identical), RN7SL239P (79% identical), RN7SL278P (79% identical), RN7SL478P (79% identical), RN7SL50P (79% identical), RN7SL655P (78% identical), RN7SL230P (78% identical), and 702 more.